CD4 (CD4 molecule)
Diseases named in the same sentence as CD4 in open-access papers (continued):
Sharing a sentence is not in itself a finding about the gene and the disease.
infection (continued). "Small percentages of IL-10-producing cells were found inside the liver CD4+ T cells on day 7 of infection and CD4+ T cells producing only IFN-γ were also found in these suspensions." (PMID 24312297, 2013). "An up-regulation of Ccl3, Ccl4, Ccl5, and Tgfb, a strong CD4+ T-cell response, and down-regulation of Il17, Il21 and Il23 occurred during infection." (PMID 23383148, 2013). "Endemic SIVcpz infection in wild chimpanzees can cause a less severe AIDS-like syndrome, with CD4+ T cell depletion, lymphatic tissue destruction, and premature death." (PMID 22945238, 2013). "HIV-1 internalization occurs through DC-SIGN in both immature and mature DCs, thus leading to enhanced infection via DC-SIGN within CD4 lymphocytes and through trans-infection." (PMID 23554973, 2013). "Although the virus follows a similar life cycle in CD4+ T lymphocytes and macrophages, the infection of both cell types shows major differences." (PMID 24009706, 2013). "Infection with intestinal helminths can result in either expulsion or development of chronic infection, often depending on the type of CD4+ T-cell response generated." (PMID 24098124, 2013). "They had a lower proportion of infection with CRF01_AE virus (68.8% vs. 78.7%, p<0.001) and higher CD4 cell counts (median 349 vs. 104 cells/mm3, p<0.001)." (PMID 23826076, 2013). "We previously reported human T cells in chronically HIV-infected BLT mice demonstrate increased PD-1 expression, and that T cell PD-1 levels in these mice correlate positively with viral loads and inversely with CD4+ cell levels, as seen in human infection." (PMID 24204962, 2013). "Growing knowledge about HIV reservoirs indicates the need to limit reservoir size and preserve the CD4 compartment as early as possible after infection." (PMID 23691172, 2013). "Herein, we demonstrate that primary CD8+ T cells from HLA-B*57/5801 elite suppressors were able to efficiently eliminate resting and activated primary CD4+ T cells shortly after viral entry and prior to productive infection." (PMID 23816179, 2013). "As result,CD4+CD8+ cells exhibit a progressive diminution of GR/PRLRexpression ratio during infection." (PMID 24324845, 2013). "CD4M33F23 is a CD4 mimetic that has been shown to be more effective than CD4 and to interact with gp120 and inhibit infection of a wide range of HIV-1 isolates." (PMID 23840383, 2013). "These markers are also associated with increased risks of both infection-related and infection unrelated cancers even after adjusting for demographics and CD4 T cell count." (PMID 24330529, 2013). "Extra-cellular infections are usually eliminated by antibodies that are generated by B cells under the control of CD4+ T helper cells." (PMID 23705941, 2013). "Instead, the infection persists for decades due to latent virus residing at least in a small pool of CD4 memory T cells (106–107/patient)." (PMID 24204950, 2013). "A population of IFN-γ-secreting CD4 T cells responding to RplF51–59, Aasf24–32, and PmpG-1303–311 was detected as early as 4 days after infection." (PMID 24204262, 2013). "Lungs were harvested at the indicated time points post-infection, and flow cytometric analysis was performed to determine the percentage of Foxp3+ cells out of the CD4+ T cell population." (PMID 23785280, 2013). "HIV-1 host genomic studies performed so far have focused on clinically defined outcomes (resistance to infection, clinical presentation, disease progression or death) or on pathogen-related laboratory results (such as CD4+ T cell counts and VL set point)." (PMID 24171102, 2013). "Here, we show that also those DCs, which sampled virions through an epithelial barrier, maintain the ability to spread the infection to CD4+ T cells for at least 4 days from infection." (PMID 23606583, 2013). "Direct contact of infected DC with CD4+ T cells forms a virologic synapse that is central to trans infection." (PMID 24278768, 2013).
infection (continued). "In the septic patients (those who already had an identified source of infection), the correlation between the changes in the percentage of BTLA+CD4+ lymphocytes and the development of a second subsequent infection during the same hospital stay was lost." (PMID 24289156, 2013). "The hemozoin-loaded DC are partially activated, leading to increased activation and trans infection of CD4+ T cells." (PMID 24278768, 2013). "The highly conserved membrane proximal external region (MPER) of the HIV-1 envelope protein gp41 plays important roles during mucosal transmission and target (CD4+) cell infection." (PMID 23506331, 2013). "Our results show infection of the monocyte population as well, though at a much lower level than CD4 T cells." (PMID 23691172, 2013). "CCR5 is a CC chemokine receptor expressed on CD8+, and CD4+ T cells are responsible for recruitment of these crucial elements of immune response to the infection sites." (PMID 24403912, 2013). "Similar Siglec-5-dependent differences were seen when comparing infection outcomes in primary CD4+ T cells from humans and chimpanzees." (PMID 22945238, 2013). "By day 28 post infection both genotypes displayed an increased number of CD4+IFN-γ+ T cells, which was more pronounced in B6.WT mice." (PMID 24205367, 2013). "HIV mutations arise primarily during the process of reverse transcription during the de novo infection of active CD4+ T cells." (PMID 23658114, 2013). "HIV-1 DNA persists in naïve CD4+ T cells in patients on suppressive cART, although the frequency of infection is approximately 1–2 logs less than in memory CD4+ T cells." (PMID 23803414, 2013). "This is the first study, to our knowledge, to demonstrate expression of both IL-17A and IL-17F in the same CD4+ T cell in a human infection." (PMID 23451159, 2013). "Protective immunity following challenge with Hp infection is known to require CD4+ T cells and worm expulsion during primary infection is defective in SCID mice." (PMID 23935505, 2013). "It took years for this phenomenon to be extended, as in 1999 Carr and colleagues reported that MDM transmitted HIV-1 to CD4+ T cells much more efficiently than cis infection of T cells." (PMID 24278768, 2013). "Hu-mice were bled every alternate week for up to 18 weeks post infection (wpi) for estimation of viral load in plasma and frequency of CD4+ T cells in the blood." (PMID 24195843, 2013). "One potential explanation for enhanced TGFβ signalling observed in CD4+ T-cells is enhanced activation of host latent TGFβ during infection." (PMID 24098124, 2013). "CD4+ T cells decreased from about 50% to below 30% in both children in the first five years of infection and the infecting R5 viruses were replaced by X4 viruses within the same period." (PMID 24156513, 2013). "Since CD4+ T cells play a crucial role in determining the outcome of disease during H. pylori infection, we sought to determine the relative contributions of effector and regulatory CD4+ T cell subsets in the gastric mucosa during infection." (PMID 24039925, 2013). "We found significant increase in the frequency and absolute numbers of IL-17A-producing CD4 T cells in the lung throughout the course of infection with B. pertussis." (PMID 23592988, 2013). "It is generally believed, from experimental SIV infection in Rhesus macaques, that the initial focus of infection occurs in resting CD4 T-cells in genital mucosa, followed very shortly by spread to lymphatic tissues." (PMID 23630526, 2013). "Our data confirm that it is possible and mandatory to assess multiple functional attributes of CD4 T cell response in the context of infection." (PMID 23383106, 2013). "It is important to note that at present, the majority of these strategies are being considered in the context of fully suppressive cART, to prevent de novo infection of newly generated/expanded target CD4 T cells." (PMID 23459797, 2013).
infection (continued). "After interaction with CD4+ T cells, mature DC (mDC) release the virions on the contact zone, which enables infection of the target cell." (PMID 23590845, 2013). "Equivalent numbers of CD4+ cells were recruited to the lungs in the two groups of mice at both 4 and 9 weeks post-infection." (PMID 23785280, 2013). "Co-incubating Cc-CD4 with HIV-1 pseudovirus representing clade C resulted in a significant inhibition of infection of TZM-bl cells." (PMID 23840383, 2013). "Between days 4 and 7 of infection, there was a significant increase in the total numbers of CD4+CXCR3−GFP+ T cells and inflammatory monocytes." (PMID 24130498, 2013). "Immunization with this vector induces good protection from FV challenge infection with strong CD4+ T cell and binding antibody responses, but significant levels of neutralizing antibodies only become detectable after FV infection." (PMID 24349306, 2013). "Following infection, dendritic cells (DCs) migrate to the draining mesenteric lymph node where they prime and activate antigen-specific CD4+ T helper (TH) cells." (PMID 23555902, 2013). "We show that, early during development of chronic infection with the murine intestinal parasite Trichuris muris, TGFβ signalling in CD4+ T-cells is induced and that antibody-mediated inhibition of TGFβ function results in protection from infection." (PMID 24098124, 2013). "It has been already established that a brief treatment of iDCs with TLR2 ligans (i.e. 1 hour) enhanced HIV-1 transfer and infection of activated CD4+ T cells by CCR5 virus." (PMID 23844079, 2013). "In a recent study, the degree of CD4 T cell recovery in children on ART was correlated with the initial (pre-ART) CD4 T cell count and the length of time between infection (at birth) and the commencement of treatment." (PMID 24273540, 2013). "Conversely, vigorous and functional CD4 T cell responses during the early phases of HCV infection correlate with subsequent control of the infection." (PMID 23717308, 2013). "Based on our findings in the mouse model we suggest that a protective vaccine against infection with M.tb should primarily possess the ability to induce (and maintain) CD4 phenotypes expressing TNF-α/IL-2." (PMID 23977248, 2013). "Neutralization of CD4+ lymphocytes by monoclonal antibodies negates H. contortus immunity and increases the parasite burden in sheep resistant to infection." (PMID 23509684, 2013). "Nef-mediated down-regulation of CD4, the major HIV receptor, prevents superinfection during the early and late stages of infection as well as formation of the viral Env protein/CD4 oligomers during the budding process." (PMID 23372701, 2013). "At 5 days post-infection, Granzyme B+CD4+ T cells up-regulated the adhesion molecule CD44, but expressed neither the co-stimulatory receptor CD27 nor the memory T cell marker CD127 (a subunit of interleukin-7 receptor-α)." (PMID 24367519, 2013). "We next evaluated the level of polyfunctional CD4 T cell subsets induced by the different vaccine regimens in order to later examine the correlation of these subsets with protection against infection with M.tb." (PMID 23977248, 2013). "Semen CD4+ T cells and macrophages were productively infected at all stages of infection and were infectious in vitro." (PMID 24348253, 2013). "In STLV-1-infected monkeys, investigators found clonal proliferation of STLV-1-infected cells and the preferential infection of CD4+ T cells by the virus." (PMID 24156738, 2013). "We have previously shown that WSX-1 signalling suppresses IFN-γ production by CD4+ T cells during this infection and that WSX-1 is essential for preventing CD4+ T cell dependent immunopathology." (PMID 23593003, 2013). "By secreting a variety of cytokines, effector CD4+ T cells can also recruit other cells including neutrophils and monocytes to the sites of infection." (PMID 23966946, 2013).
infection (continued). "On average, IL-7 25 ng/mL increased the fractions of HIV-1-infected CD4+ (CD8− p24gag+) T cells 3.0±0.9 fold on day 9 post infection (n = 5, p<0.05)." (PMID 23408885, 2013). "These samples were from individuals with a broad range of infection times who had CD4 cell count data available from the time of sample collection." (PMID 24236054, 2013). "Quantitative gene expression analysis with real-time RT-PCR showed that DRAM expression was increased on days 4 and 5 post-infection in HIV-infected CD4+ T cells." (PMID 23658518, 2013). "IL-7 25 ng/mL increased Bcl-2 expression in HIV-1-infected CD4+ T cells on average 1.5±0.1 fold on day 9 post infection, compared with donor-matched infected untreated tissues (n = 4, p<0.05)." (PMID 23408885, 2013). "The number of CD4+ T cells in peripheral blood rapidly and transiently declined at day 11 post infection before rebounding and then steadily declining in untreated macaques." (PMID 23935491, 2013). "We demonstrated that purified CD4+ T cells lose the ability to proliferate and produce Th2 cytokines to parasite antigen as infection progresses." (PMID 23516361, 2013). "After eliminating CD4- or CD8-positive T-cells all immunized mice survived the challenge infection, and after simultaneous removal of both T-cell subsets still 7 out of 8 mice resisted the challenge." (PMID 24376753, 2013). "When CD4+T cells were treated with E2 prior to infection (pre) for 3 days, released p24 was significantly reduced 7 days after infection with HIV-1BaL (56% reduction; p = 0.024)." (PMID 23614015, 2013). "Concerning, however, was the finding that plasma viremia remained relatively high (albeit significantly reduced) despite the significant increase in infection resistant CD4+ T-cells in all studies." (PMID 24287598, 2013). "Infection of resting CD4 T-cells is inefficient due to many factors including low CCR5 expression, cytoskeletal barriers, limiting levels of deoxynucleoside triphosphates (dNTPs) due to SAMHD1, and inefficient nuclear import and integration." (PMID 23375003, 2013). "Quantification of SIV DNA copies in sorted semen CD4+ T cells and macrophages at various stages of infection." (PMID 24348253, 2013). "This has led to a widely accepted conclusion that the infection of gut CD4+ T cells is the origin of the initial burst of viremia, generating the peak viral load in plasma, and a major contributor to viral production during infection." (PMID 24119218, 2013). "Early mortality during HAART is dependent on treatment CD4 threshold until 6 years post infection and becomes dependent on diagnosis delay after 6 years post infection." (PMID 23308161, 2013). "Although LP-BM5 infection also induces lymphoproliferation within secondary lymphoid organs, we detected a sharp decline in circulating CD4+ and CD8+ T-cells." (PMID 23902750, 2013). "The R2 Env has been reported to mediate CD4-independent infection and to induce a cross-reactive, albeit low potency, neutralizing antibody response." (PMID 23533650, 2013). "Altogether, these results suggest that CD4+ help in mobilizing effector CD8+ T cells to the site of infection, which contributes to proper control of the dissemination of HSV-1 into the CNS." (PMID 24068938, 2013). "To specifically test the role of CD4+ T-cells in protection from infection observed in Itgb8 (CD11c-Cre) mice, we depleted CD4+ T-cells using an anti-CD4 antibody." (PMID 24098124, 2013). "Leukocytes in lymph nodes from infected and non-infected WT, PMN-depleted and Genista mice were analyzed by flow cytometry at 8 and 15 days of infection using CD4+/CD44+, CD8+/CD44+, B220+/CD95+, and CD11b+/Ly6C+ cell markers." (PMID 23458832, 2013). "As expected, RAG+CD4+CD8 mice developed small nodules that resolved within 7 weeks following infection." (PMID 23874205, 2013).
infection (continued). "This is a qualitative rather than a quantitative assay that provides a general overview of the quality and function of HCV-specific CD4 T cells during different stages of infection." (PMID 23818845, 2013). "While CD4 counts are a very noisy and unreliable indicator of time since infection on an individual basis, aggregated CD4 counts follow an almost linear trend." (PMID 24339751, 2013). "Salmonella-specific IFNγ+ Tbet+ CD4 T cells were first detected at 8 days post-infection and expanded continuously through 30 days post-infection." (PMID 23754944, 2013). "Semen CD4+ T cells were strongly and persistently depleted (2.50%±0.78%), from primary infection onwards (Mann-Whitney test, p = 0.0076 and 0.0077, respectively)." (PMID 24348253, 2013). "More recently, we reported that the frequency of CD137+ CD4+ T cells is increased in the bone marrow of mice experiencing acute inflammation or infections, and that these T cells induce myeloid differentiation of the bone marrow cells." (PMID 23945137, 2013). "The significant decrease (p<0.01) of the Brucella bacterial load from 8 days post-infection onwards correlated with a very strong T cell response, a large Granzyme B-expressing CD4+ T cell population and a diminution of IFN-γ secretion." (PMID 24367519, 2013). "Each subset contribution to the pool of infected resting CD4 T cells was then calculated by taking into account the infection level and frequency in blood of each." (PMID 23691172, 2013). "In simian immunodeficiency virus (SIV)-infected rhesus macaques, most infected cells identified during early infection (i.e. the time of reservoir formation) were found to be resting CD4 T-cells." (PMID 23375003, 2013). "We found that RRV-infected NOD mice maintain thymic Treg production at day 21 post infection when CD4+ Teff and other thymocyte subsets are reduced." (PMID 23554993, 2013). "Previous published observations indicate that resting CD4+ T cells are refractory to productive infection with HIV-1 and the mechanism(s) at play and its cellular mediators have still remained elusive." (PMID 23844079, 2013). "When C. crescentus expressing CD4 or MIP1α were combined, a significant increase in protection from infection occurs." (PMID 23840383, 2013). "The factors that serve to restrain CD4 independence during normal infection, and their relationship to coreceptor use and entry, have important implications for cell targeting and tropism in vivo." (PMID 24219995, 2013). "Despite the contrasting clinical conditions at birth, major CD4 depletion and disease progression occurred in both children in the first 5 years of infection." (PMID 24156513, 2013). "They showed that HIV-1 R5 infection was first established independently in both intraepithelial CD4+ T and LC through a CCR5 binding pathway." (PMID 24278768, 2013). "Several other models involve direct infection of either untreated or chemokine-treated resting CD4 T-cells and result in up to a few percent of cells becoming latently infected, reflecting the preferential infection of activated cells." (PMID 23375003, 2013). "In our simulations, A3G-augmented stem cell therapy (A3G-SCT) is introduced on day 100 after initial infection by changing the production of uninfected CD4+ T cells in thymus to generate both WT and A3G-augmented CD4+ T cells with the ratio of 1-f:f." (PMID 23724012, 2013). "We show a higher infection frequency in memory CD4+ T-cells compared to naïve T-cells from lymph node tissue." (PMID 23818847, 2013). "Infection of rhesus macaques with SIV results in high acute plasma viral loads and rapid loss of mucosal CD4+ T cells." (PMID 23593167, 2013). "There is plenty of evidences that to spread the infection the DCs transfer virus to CD4+ T cells, which sustain actively viral replication, via both vesicular uptake (called trans infection) and de novo production (called cis infection)." (PMID 23606583, 2013).